FABP4 (fatty acid binding protein 4)
Diseases named in the same sentence as FABP4 in open-access papers (continued):
Sharing a sentence is not in itself a finding about the gene and the disease.
COVID-19 (18 papers, 2020 to 2025). A disease caused by infection with severe acute respiratory syndrome coronavirus 2. "Low levels of fatty acid-binding protein 4 (FABP4) in BALF macrophages of patients suffering from severe COVID-19 have been linked to declining lung function." (PMID 35438176, 2022). "FABP4 was significantly correlated with “immune response_lectin-induced complement pathway”, “immune response_classical complement pathway”, and “COVID-19-associated coagulopathy” in the development of CRC." (PMID 34680577, 2021). "Patients with devere and mild COVID-19 exhibited substantial reduction in the expression of FABP4, APOC1, APOE, C1QB, and NURP1, all associated with interstitial and macrophage cluster-0." (PMID 33138195, 2020). "It is possible that adipocytes in their native tissue environment respond differently to infection, or that FABP4 secretion in vivo is elicited as a response to more complex systemic interactions, particularly those associated with the pathophysiology of severe COVID-19." (PMID 39843629, 2025). "We observed elevated FABP4 levels in the lungs and circulation of COVID-19 patients, which strongly correlated with disease severity." (PMID 39843629, 2025). "We establish FABP4’s importance in two separate human COVID-19 cohorts and demonstrate, through in vitro studies, that targeting FABP4 effectively reduces viral titers in multiple cell types and viral strains." (PMID 39843629, 2025). "In this study, we observed significantly elevated FABP4 levels in the serum and lungs of COVID-19 patients that highly correlate with disease severity." (PMID 39843629, 2025). "There was also downregulation of lipid metabolism-associated genes (FABP4, APOC1, APOE, MARCO) in COVID-19 effector CD8+Tcs." (PMID 37029220, 2023). "FABP4 was preferentially expressed in healthy controls and in patients with moderate COVID-19, while FCN1 and SPP1 were expressed in patients with severe COVID-19." (PMID 32612615, 2020). "Interestingly, FABP4+ macrophage populations were significantly reduced in the bronchoalveolar lavage fluid of COVID-19 patients with severe disease compared to both controls and patients with moderate disease." (PMID 39843629, 2025). "Interestingly, although macrophages were also present in healthy subjects and patients with mild COVID-19, they had different gene signatures, indicative of interstitial and cluster-0 macrophage (i.e., FABP4, APOC1, APOE, C1QB, and NURP1)." (PMID 33138195, 2020). "Consequently, the impact of targeting FABP4 on the overall pathogenesis of COVID-19, and the protection that such interventions may offer to individuals with underlying metabolic conditions, may not be limited to the reduction in viral titers." (PMID 39843629, 2025). "To assess FABP4’s involvement in SARS-CoV-2 infection, we conducted immunohistochemical staining for FABP4 in lung biopsies obtained from individuals with COVID-19." (PMID 39843629, 2025). "GSEA of the gene sets that characterize tissue-resident alveolar macrophages in severe COVID-19, namely AMØ1 (EGAS00001005634), TRAM1+ (GSE155249), and FABP4+ (GSE145926) on the ranked comparison of the transcriptomes of CHIR-AMØ vs. DMSO-AMØ." (PMID 40365863, 2025). "The scRNAseq data show that, in healthy human BALF, the FABP4+ macrophages express the TAM receptor AXL and the ligand for the TAM receptor MerTK (PROS1) and that these were profoundly repressed in severe COVID-19." (PMID 34143756, 2021). "Macrophage subset classification markers, including FCN1, SPP1, and FABP4, were differentially expressed by circulating and BALF monocyte-macrophages from patients with mild or severe COVID-19." (PMID 33101705, 2020). "Our study highlights fatty acid-binding protein 4 (FABP4), a key regulator of metabolic dysfunction and inflammation, as a modulator of SARS-CoV-2 pathogenesis, correlating strongly with disease severity in COVID-19 patients." (PMID 39843629, 2025).
COVID-19 (continued). "Together, these data indicate that FABP4 facilitates SARS-CoV-2 infection and that therapeutic targeting of FABP4 may be a beneficial treatment strategy for mitigating COVID-19 severity and mortality in humans." (PMID 39843629, 2025). "In contrast, COVID-19 patients with milder respiratory distress were characterized by increased plasma levels of the inflammation-resolving, antithrombotic cytokine PROS1, which characterized the resident AM FABP4+ cluster." (PMID 34143756, 2021). "Macrophages with FABP4, known as the alveolar macrophages, were reduced while macrophages with FCN1 and SPP1, considered as the monocyte-derived proinflammatory macrophages, were strikingly increased in COVID-19 patients." (PMID 33762651, 2021).
ovarian tumors (18 papers, 2012 to 2024). "We then studied the expression of FABP4 in vessels of high-grade primary ovarian tumours and omental metastasis in more detail, focusing on the intratumoural distribution of FABP4-positive vessels." (PMID 27568980, 2017). "Angiogenesis, growth and metastasis in ovarian tumour xenografts were markedly inhibited by therapeutic siRNA delivery targeting mouse endothelial FABP4." (PMID 27568980, 2017). "Moreover, overexpression of fatty acid-binding protein 4 (FABP4) was observed in different cancers, e.g., prostate, bladder, renal cell carcinoma and also ovarian neoplasms." (PMID 33809784, 2021). "Interestingly, our data are supported by a recent study showing that endothelial FABP4 targeting by siRNA exerts antiangiogenic and antitumor effects in an ovarian tumor xenograft model." (PMID 30575815, 2019). "Moreover, omental metastases were characterized by higher expression of fatty acid-binding protein 4 (FABP4) than primary ovarian tumors." (PMID 28956065, 2018). "Inhibition of FABP4 by small molecules reduced lipid accumulation in cancer cells in co-culture experiments with adipocytes, and Fabp4−/− mice presented significantly reduced ovarian tumor growth." (PMID 28915700, 2017). "Notably, FABP4 is a reported target of VEGF/VEGFR2 axis, has been implicated in angiogenesis associated with glioblastoma aggressiveness, and its deficiency in mice has inhibitory effects on ovarian tumor vasculature." (PMID 24240026, 2013). "The future study will examine the relationship between PTGIS and lipid metabolism molecules such as PPAR, FABP4, FASN, and CD36, as well as the effect of fatty acid metabolism on the growth and invasion of ovarian tumorous cells." (PMID 36785673, 2023). "We show that endothelial FABP4 expression requires NOTCH1 and VEGFA signalling, and is required for ovarian tumour angiogenesis." (PMID 27568980, 2017). "Additionally, upregulation of fatty acid-binding protein 4 (FABP4, also known as aP2) was observed in omental metastases compared to primary ovarian tumors." (PMID 36670988, 2023).
chronic kidney disease (17 papers, 2011 to 2026). Impairment of the renal function secondary to chronic kidney damage persisting for three or more months. "In a separate study, an association was identified between FABP4 and a prolonged QTc interval in patients with stable angina pectoris and chronic kidney disease." (PMID 40898929, 2026). "Conversely, in patients with stable angina and chronic kidney disease, male sex was associated with higher plasma FABP4 levels." (PMID 35955575, 2022). "FABP4 has been associated with adiposity and metabolic disorders, and it has been reported to be a novel predictor of cardiovascular mortality in end-stage renal disease." (PMID 31234795, 2019). "The aim of this study was to investigate whether plasma FABP4 level is associated with a prolonged QT interval by analyzing 12-lead electrocardiograms (ECGs) in patients with stable angina and chronic kidney disease (CKD)." (PMID 31234795, 2019). "In the present study, we hypothesized that serum FABP4 is a novel marker for risk stratification of end-stage renal disease (ESRD) patients on hemodialysis (HD)." (PMID 22102888, 2011). "Women with atrial fibrillation or coronary atherosclerosis present higher plasma FABP4 levels, whereas women with stable angina and chronic kidney disease exhibit reduced plasma FABP4." (PMID 35955575, 2022). "Biopsy specimens of chronic kidney disease patients and kidneys subjected to unilateral ureteral obstruction (UUO) of FABP4-deficient mice or FABP4 inhibitor-treated mice were collected for the investigation of FABP4 mediating MMT of RIF." (PMID 33101287, 2020). "Taking these into consideration, FABP4 appears to be accumulated in circulation due to diminished renal excretion in chronic kidney disease." (PMID 22102888, 2011). "A similar study in 1316 patients with chronic kidney disease also showed that FABP4 levels, ascertained using the multiplex proximity extension assay (PEA) technique, were associated with secondary major cardiovascular events (MACE); however, this could not be replicated in a cohort of 300 patients." (PMID 38698167, 2024). "Studies also confirmed that circulating FABP4 depended on renal function in chronic kidney disease (CKD) and acute kidney injury (AKI) patients." (PMID 35541316, 2018).
hyperlipidemia (16 papers, 2010 to 2026). "Meanwhile, previous studies have shown that treatment with atorvastatin can reduce the serum level of FABP-4 in patients with hyperlipidemia." (PMID 38024104, 2023). "In comparison to the control group, the CAD group took more medications, and previous research showed that treatment with atorvastatin can reduce serum FABP4 levels in patients with hyperlipidemia." (PMID 33287461, 2020). "In the present study, the observed activation of SREBP-1c and FABP-4 levels may be beneficial in significant uptake of circulatory fatty acid ends with reduced hyperlipidemia and metabolic inflammation." (PMID 35209178, 2022). "Consequently, these findings imply that CD34+ cells may be involved in fibrosis through their differentiation into FABP4+ fibroblasts, which distinguishes them from other cardiac fibroblasts involved in cardiac remodeling in lipid metabolism disorders (hyperlipidemia)." (PMID 39198543, 2024). "Alisol A treatment was able to improve the parameters of hyperlipidemia, including plasma total cholesterol, triglycerides, LDL‐C, NEFA and FABP4." (PMID 31144451, 2019). "In addition, hyperlipidemia was improved in GIOP rats after calcium supplement treatment for 12 weeks, and our results showed that calcium gluconate had a comparatively faint inhibition to the expressions of PPAR-γ and FABP4." (PMID 26941827, 2016). "Taken together, these results show that Crif1f/+,Fabp4 mice have mildly reduced primary OXPHOS deficiency in adipose tissue but, unlike the lipodystrophic model, they show no defects in adipose tissue development, and no hyperlipidemia or ectopic lipid accumulation." (PMID 23516375, 2013). "Through the integration of bone marrow transplantation models and lineage tracing, our study showed that hyperlipidemia can expedite the differentiation of non-bone marrow-derived CD34+ cells into fibroblasts, particularly FABP4+ fibroblasts, in response to angiotensin II." (PMID 39198543, 2024).
steatosis (16 papers, 2017 to 2025). Increased lipid within the cytoplasm of cells. "To further confirm the specificity of FABP4 in MASLD-HCC, we compared serum samples from patients with steatosis, HBV-associated HCC, and MASLD-induced HCC." (PMID 41392988, 2025). "Six progress-related genes (AKR1B10/SPP1/CD24/UBD/FABP4/STMN2) were found remarkably correlated with steatosis, ballooning, inflammation, fibrosis, and NAS in the progress of Normal/NAFL/NASH." (PMID 33574818, 2020). "Concomitant with the increase in PPARγ2 expression, overexpressing JMJD2B stimulated the expression of hepatosteatosis genes including fatty acid uptake-associated genes CD36, FABP4 and lipid droplet-associated genes PLIN2, CIDEC in HepG2 cells, which are known PPARγ2 steatosis target genes." (PMID 30214048, 2018). "Furthermore, palmitate activation via FABP4 triggers hepatocellular apoptosis via altered phospholipid composition and steatosis by acylation into complex lipids." (PMID 28933365, 2017). "The heatmap shows the relative expression levels of the four genes (AKR1B10, FABP4, GNMT, and THBS1) in normal, steatosis, and steatohepatitis tissues across the three training datasets." (PMID 39781352, 2025). "Our results indicated that serum FABP4 levels were significantly elevated in MASLD-HCC patients, with a mean level of 16.24 ng/mL, compared with both the HBV-HCC and steatosis groups." (PMID 41392988, 2025). "In our in-house MASLD-HCC mouse model, Fabp4 mRNA levels were significantly upregulated in MASLD-HCC, showing a gradient increase from steatosis to MASH and subsequently to HCC." (PMID 41392988, 2025). "Previous studies have reported increased FABP4 mRNA expression and FABP4 protein in the culture medium using in vitro models of EtOH- and fat-induced cell steatosis, and in animal models of ALD and NAFLD, increased hepatic FABP4 mRNA and serum FABP4." (PMID 36358315, 2022). "The anti-steatosis effects of myeloid GPSM1 knockout were presumably attributed to downregulation of fatty acid uptake genes (CD36, FABP4) and upregulation of fatty acid β-oxidation genes (LCAD) in the liver." (PMID 36434066, 2022). "The analysis of genes identified in NAFL-Steatosis patients and NAFL-NASH patients (n = 58 genes) and in NASH patients (n = 141 genes) with high MMP9 level showed that 4 genes, FABP4, MMP9, HELLS and TREM2, were shared between these three groups of patients." (PMID 31874999, 2019). "Concomitant with reduced PPARγ2 expression, the expression of its steatosis target genes including CD36, FABP4 and PLIN2, CIDEC was also reduced." (PMID 30214048, 2018). "Furthermore, FABP4 concentrations did not correlate with the inflammation, steatosis or ballooning score (P-values: inflammation = 0.08; steatosis = 0.19; ballooning = 0.2)." (PMID 36609276, 2023). "Still, abundant steatosis is not an immediate outcome of the highly increased expression level of PPARG, FABP4, CD36, and LPL in the liver of the severly obese minipigs." (PMID 32205840, 2020).
coronary atherosclerosis (15 papers, 2011 to 2022). Atherosclerosis of the coronary vasculature. "Results from the clinical studies showed an increased FABP4 plasma level in the female gender in several pathological conditions such as coronary atherosclerosis or atrial fibrillation." (PMID 35955575, 2022). "It has recently been demonstrated that FABP4 is present both on coronary endothelium and in cardiomyocytes and significantly contributes to the induction and progression of coronary atherosclerosis." (PMID 31979197, 2020). "This highlights that the role of FABP4 in the myocardium in coronary atherosclerosis remains unchanged." (PMID 31979197, 2020). "Coronary atherosclerosis resulted in a 50.8% increase in FABP4 mRNA and a 19.3% increase in its protein content, although the statistical significance was achieved solely in the case of protein." (PMID 31979197, 2020). "Therefore, FABP4 produced in epicardial/perivascular fat and macrophages within the atherosclerotic lesion upregulates inflammation-related pathways, leading to the development of coronary atherosclerosis." (PMID 35955575, 2022). "Furthermore, FABP4 could be locally produced by the perivascular fat and macrophages in the vascular plaques and contributed to the development of coronary atherosclerosis." (PMID 34789046, 2021). "We demonstrated that in myocardium coronary atherosclerosis increases only the transcript level of G0S2 and FABP4." (PMID 31979197, 2020). "Considered as pro-inflammatory adipocytokine fatty acid binding protein 4 (FABP4) is locally produced by both EAT and macrophages in vascular plaques and may promote development of coronary atherosclerosis." (PMID 34609443, 2021).
Nephropathy (15 papers, 2011 to 2025). A nonspecific term referring to disease or damage of the kidneys. "Expression of FABP4 has been demonstrated in the kidney of CKD patients and the expression is associated with renal dysfunction, while urinary FABP4 has been proposed as an early biomarker of kidney damage." (PMID 39968160, 2025). "We also identified genes previously linked to kidney disease, such as fatty acid binding protein 4 (FABP4, log2FC = 5.69), trefoil factor 3 (TFF3, log2FC = 5.58), and angiopoietin 2 (ANGPT2, log2FC = 2.46)." (PMID 40663403, 2025). "A previous study reported that ectopic FABP4 expression in the glomerulus was induced by kidney diseases and was closely associated with proteinuria." (PMID 33101287, 2020). "Previous studies have reported that increased FABP4 levels were associated with the deterioration in renal function in both humans and animals and therefore served as an independent indicator for the progression of nephropathy." (PMID 29992142, 2018). "There was growing evidence for the role of FABP4 in various types of kidney diseases such as ischemia/reperfusion, rhabdomyolysis, and cisplatin-induced AKI in mice." (PMID 33101287, 2020). "In the present study, we reported pharmacological effect of FABP4 in a murine kidney disease model of glycerol-induced rhabdomyolysis." (PMID 30135658, 2018). "The links between inflammatory pathways and ER stress are of great interest in kidney diseases and understanding the intricate links and identification of drug target FABP4 are crucial for developing effective therapeutics against renal disease cluster." (PMID 30135658, 2018). "Growing evidence suggests that fatty acid-binding protein 4 (FABP4) is critically involved in kidney diseases, while its role in septic AKI remains unknown." (PMID 35410456, 2022). "However, the clinical significance of FABP4 in fibrotic kidney disease remains to be determined and little is known of the potential relationship of MMT or FABP4 signaling in renal fibrosis." (PMID 33101287, 2020). "Their findings raised the possibility that FABP4 might be used as a serum biomarker for stratifying nephropathy stages in patients with T2DM." (PMID 30857223, 2019). "Furthermore, the prognostic value of FABP4 for kidney damage and cardiac contractile dysfunction in patients with T2DM have also been proposed." (PMID 30857223, 2019). "In the control subjects, FABP4 levels were negatively correlated with estimated glomerular filtration rate (data not shown), which is an index of renal function, as previously reported in DM patients with nephropathy." (PMID 22102888, 2011). "The level of U-FABP4 was independently associated with levels of proteinuria and eGFR in patients with kidney disease, and the association of U-FABP4 with proteinuria or eGFR was independent of circulating FABP4 and U-FABP1, which reflects damage of proximal tubular epithelial cells." (PMID 33143633, 2020).